PGR (progesterone receptor)
Diseases named in the same sentence as PGR in open-access papers (continued):
Sharing a sentence is not in itself a finding about the gene and the disease.
breast cancer (continued). "Among the four molecular subtypes of breast cancer, estrogen receptor (ER) and/or progesterone receptor (PR) + and human epidermal growth factor receptor 2 (HER2)− occurred most commonly and account for approximately 60% of breast cancer patients." (PMID 36224558, 2022). "Breast cancer is classified into four molecular types based on the expression of estrogen receptor (ER), progesterone receptor (PR), human epidermal growth factor receptor-2 (HER-2) and Ki-67 in breast cancer." (PMID 36612100, 2022). "TNBC, a specific subtype of breast cancer characterized by lack expression of estrogen receptor (ER), progesterone receptor (PR), and human epidermal growth factor receptor 2 (HER2), makes up approximately 15% of all breast cancers." (PMID 35148751, 2022). "Triple-negative breast cancer (TNBrCa) (ER−/PgR−/HER2−) preferentially affects young women and accounts for 12–17% of all breast cancers." (PMID 35158842, 2022). "In breast cancer cells, the elevated expression level of TMED3 was significantly correlated with the level of estrogen receptor, progesterone receptor and human epidermal growth factor receptor-2, as well as the status of lymph nodes metastasis." (PMID 35854294, 2022). "The estrogen receptor (ER), progesterone receptor (PR), and human epidermal growth factor receptor 2 (HER2) represent critical pathways for tumor growth and replication of breast cancer cells." (PMID 35006257, 2022). "In breast carcinoma, NUCKS1 exhibited higher expression than other investigated markers (including Ki67, estrogen receptor, progesterone receptor, human epidermal growth factor receptor 2, and cytokeratin 5/6)." (PMID 35069784, 2022). "Breast cancer is classified based on expression of receptors which include estrogen receptor (ER), human epidermal growth factor (ERBB2) and progesterone receptor (PR)." (PMID 33670942, 2021). "Approximately 15% of breast cancers are defined as triple-negative breast cancer (TNBC), which lacks expression of the estrogen receptor (ER) and progesterone receptor (PR) and lacks overexpression of human epidermal growth factor 2 (HER2)." (PMID 34211613, 2021). "Estrogen receptor (ER), progesterone receptor (PR) and human epidermal growth factor receptor-2 (HER2) are the most important prognostic and predictive markers for determining the appropriate breast cancer treatment." (PMID 34513690, 2021). "Regarding MCF10DCIS.com, we observed lower expression of the proliferation markers, when compared to the breast cancer cell lines, and low GSTM1 and PGR expression." (PMID 34238275, 2021). "The distribution of breast cancer stages was: 10.3% stage 0, 41.4% stage I, 37.9% stage II, and 10.3% stage III, and 83% were estrogen receptor positive, 70% were progesterone receptor positive, and 17% were human epidermal growth factor receptor 2 positive." (PMID 34380488, 2021). "A point-of-care mRNA STRAT4 breast cancer assay for ESR1, PGR, ERBB2, and MKi67, for use on the GeneXpert platform, has been recently validated on tissues from internationally accredited laboratories, showing excellent concordance with IHC." (PMID 34050358, 2021). "At present, there are several predictive biomarkers for breast cancer, for example, triple-negative breast cancers (TNBC) which lack estrogen receptor (ER-), progesterone receptor (PR-), and amplification of human epidermal growth factor receptor 2 (HER2-)." (PMID 33959662, 2021). "The trials compare the use of multigene tests with the clinical practice, evaluating the adjuvant chemotherapy in patients with early breast cancer (stage I, II or III operable) with 0–3 positives nodes, ER+ (and/or PgR-positive) and HER2-." (PMID 33953847, 2021). "Four biomarkers [estrogen receptor (ER), progesterone receptor (PgR), Ki-67, and HER2], are used to stratify breast cancer (BC) into subtypes predictive of therapy response." (PMID 34572945, 2021).
breast cancer (continued). "TNBCs lack expression of the estrogen receptor (ER), progesterone receptor (PR), and HER2, and have a poorer prognosis than luminal breast cancer." (PMID 33541373, 2021). "We compared the efficiency of various proteomic techniques to determine routinely measured breast cancer biomarkers, including ESR1, PGR, HER2, and MKI67." (PMID 34408238, 2021). "We subsequently evaluated the status of estrogen receptor (ER), progesterone receptor (PR), and human epidermal growth factor receptor 2 (HER2), the most common biomarkers for breast cancer, and Ki‐67 on the organoids and matched tumors." (PMID 34605222, 2021). "Compared to patients with breast cancer who had higher TIL densities, those with lower densities more frequently had skin infiltration (p = 0.005), ER positivity (p < 0.001), PgR positivity (p < 0.001), HER2 negativity (p = 0.015), and lower Ki67 (p < 0.001)." (PMID 34670511, 2021). "The basic status of the estrogen receptor (ER), progesterone receptor (PR), and human epidermal growth factor receptor 2 (HER2) play a crucial role in molecular subtypes of breast cancer." (PMID 34760348, 2021). "As a subtype of breast cancer with complex heterogeneity, TNBC lacks estrogen receptor, progesterone receptor, and human epidermal growth factor receptor expression in the hormone level, which increases the difficulty of treatment." (PMID 34858165, 2021). "Breast cancer subtypes are generally classified based on the expression of the estrogen receptor (ESR1), progesterone receptor (PGR), or the human epidermal growth factor receptor 2 (HER2)." (PMID 33985544, 2021). "In molecular subtypes of breast cancer, the estrogen receptor (ER) status, progesterone receptor (PR) status, Ki-67 status, and human epidermal growth factor receptor-2 (HER-2) status are also critical for the prognosis of breast cancer." (PMID 33859986, 2021). "We found that an estradiol-challenge test that monitors an increase in tumor PgR by FFNP-PET can rapidly and accurately predict response or lack thereof to subsequent ET in patients with advanced ER+ breast cancer." (PMID 33531464, 2021). "The second patient was a 48-year-old woman with ER +, PgR +, HER2-negative breast cancer, previously treated with adjuvant cyclophosphamide and tamoxifen, taselisib and letrozole, adriamycin, and palliative radiation therapy to the lumbar spine." (PMID 34407844, 2021). "Based on the status of the tumor receptors, three types of breast cancers have been reported: estrogen/progesterone receptor-positive (ER+), human epidermal growth factor receptor 2-positive (HER2+), and triple-negative (TNBC) breast cancer." (PMID 33747948, 2021). "Metroxyprogesterone acetate (MPA), a first-generation progestin and a PgR agonist, is another treatment option; however, MPA also has binding affinity for other steroid receptors such as AR, and the anti-tumor mechanism in breast cancer is still unclear." (PMID 34070471, 2021). "Breast cancers are categorized into ER+, ER+/HER2-, HER2+ and Triple-negative subtypes based on the expression of estrogen receptor (ER), progesterone receptor (PR) and human epidermal growth factor receptor 2 (HER2)." (PMID 34956313, 2021). "The PGR (progesterone receptor), BCL2 Apoptosis Regulator and SCUBE2 (Signal Peptide, CUB Domain And EGF Like Domain Containing 2) are known to be a favorable prognostic marker on breast cancer recurrence." (PMID 34462515, 2021). "TNBC lack expression of the estrogen receptor (ER), progesterone receptor (PR), and human epidermal growth factor receptor 2 (HER2), and it is considered as the most aggressive type of breast cancers." (PMID 34208013, 2021). "In the present study, we used a popular breast cancer cell line MCF-7 as a model because MCF-7 cell line has positive estrogen receptor (ER) and progesterone receptor (PR), which are excellent targets for chemotherapy." (PMID 34696661, 2021).
breast cancer (continued). "Among the top hits, the PGR (progesterone receptor), GREB1 (growth regulation by estrogen in breast cancer 1), and BECN1 mRNAs were validated." (PMID 33542201, 2021). "Accounting for 15–20% of breast cancer, triple-negative breast cancer (TNBC) subtype lacks estrogen receptor, progesterone receptor (PgR), and human epidermal growth factor receptor 2 (HER2) expression and has a poor prognosis." (PMID 34021125, 2021). "The second study reported high inter-site and intra-site reproducibility of ESR1, PGR, ERBB2, and MKi67 mRNA measurements with the MammaTyper® test and showed a precise and reproducible assessment of the four breast cancer biomarkers." (PMID 34371382, 2021). "According to bc-GenExMiner v4.3, estrogen receptor or progesterone receptor-positive (IHC) breast cancer patients were with higher PTPRT levels, while HER2+ (IHC) breast cancer patients were with lower PTPRT level." (PMID 34414233, 2021). "Taken together, Xpert® Breast Cancer STRAT4 mRNA testing for ESR1, PGR, ERBB2, and MKI67 demonstrated good performance when compared to the diagnostic gold standard IHC/ISH." (PMID 34572945, 2021). "Prior to this clinical study, we evaluated changes in PgR levels monitored by FFNP-PET in an ER+, hormone-responsive mouse mammary cancer model." (PMID 33531464, 2021). "The PGR, ESR1 and CCND1 genes were downregulated when NRIP1 was silenced, indicating the possible role of NRIP1 in breast cancer development." (PMID 34707101, 2021). "According to histological and molecular findings, BC is divided into 3 types, namely, hormone receptor-positive EC (progesterone receptor (PR+) and estrogen receptor (ER+)), human epidermal receptor 2-positive EC (HER2+), or triple-negative breast cancer (TNBC, ER-, PR-, HER2-)." (PMID 34563186, 2021). "Based on the status of estrogen receptor (ER), progesterone receptor (PR) and receptor tyrosine-protein kinase erbB-2 (HER2), breast cancer is classified as Luminal A, Luminal B, HER2-positive (HER2-E) and triple-negative breast cancer (TNBC) subtypes." (PMID 34395234, 2021). "LMTK3 knockdown strongly reduced the expression of TFF1 in the primary screen, in addition to GREB1 (growth regulation by oestrogen in breast cancer 1) and PGR (progesterone receptor) secondary screens." (PMID 34582708, 2021). "Breast cancer clinical treatment selection is based on the immunohistochemical determination of four protein biomarkers: ESR1, PGR, HER2, and MKI67." (PMID 34408238, 2021). "In particular, a subtype of breast cancer, triple-negative breast cancer (TNBC), lacks the expression of estrogen receptor, progesterone receptor, and human epidermal growth factor receptor-2 (HER-2) and accounts for 15% of all breast cancer cases." (PMID 33912463, 2021). "With the increasing availability of facilities for IHC testing and also the affordable costs, the evaluation of estrogen receptor, progesterone receptor, and HER2/neu receptor status has become a standard routine in the management of breast carcinoma." (PMID 34912627, 2021). "Based on the expression of estrogen receptor (ER), progesterone receptor (PR), and human epidermal growth factor receptor 2 (HER 2) in tumor cells, breast cancer can be divided into multiple subtypes." (PMID 32318339, 2020). "Estrogen receptor (ER), progesterone receptor (PR), human epidermal growth factor receptor 2 (HER2), and Ki67 are the known prognostic and predictive markers for breast cancer." (PMID 32237061, 2020). "This comprehensive dataset included many established biomarkers for breast cancer, including the receptor tyrosine kinase erbB-2 (HER2), estrogen receptor (ESR1), progesterone receptor (PGR), and androgen receptor (AR)." (PMID 32489334, 2020). "The nuclear receptors (NRs) ER and PgR play critical roles in steroid hormone signaling, as well as the development and progression of both NR+ and/or HER2+ breast cancer." (PMID 35582612, 2020).
breast cancer (continued). "Especially, the distributions of estrogen receptor (ER), progesterone receptor (PR), and human epidermal growth factor receptor 2 (HER2) influence the metastatic potential of breast cancer." (PMID 32708855, 2020). "The expression of estrogen receptor (ER), progesterone receptor (PgR), and HER2 are crucial in the assessment of breast cancer specimens due to their prognostic and predictive significance." (PMID 32825530, 2020). "Triple-negative breast cancer (TNBC), characterized by the absence or low expression of estrogen receptor (ER), progesterone receptor (PR), and human epidermal growth factor receptor (HER2), is the most aggressive subtype of breast cancer." (PMID 32846967, 2020). "The status of ER, progesterone receptor (PR) and HER2 between the primary and liver metastatic tumors of breast cancer can be changed after treatment." (PMID 33489906, 2020). "Triple-negative breast cancer (TNBC) is a breast cancer subtype that lacks expression of estrogen receptor (ER), progesterone receptor, and human epidermal growth factor receptor 2 (HER2), with a diagnosis rate of 15–20% in breast cancer patients." (PMID 32457491, 2020). "Estrogen (ER) and progesterone (PgR) receptors and HER2 are crucial in the assessment of breast cancer specimens due to their prognostic and predictive significance." (PMID 32825530, 2020). "These alterations occur in approximately 35% of triple-negative and 45% of ER/PgR-positive, HER2-negative breast cancers." (PMID 32605126, 2020). "Triple-negative breast cancer (TNBC) is a subtype of breast cancer that lacks detectable expression of estrogen receptor (ER), human epidermal growth factor receptor 2 (HER2), and progesterone receptor (PR)." (PMID 32759815, 2020). "Among all the subtypes, triple negative breast cancer (TNBC), which lacks estrogen receptor (ER), progesterone receptor (PR) and HER2 expression, are the most metastatic and challenging subtype of breast cancer to treat." (PMID 33457450, 2020). "The Cox regression model for multivariate analysis of biomarkers expression indicated that PgR, Ki67, and MUC1 were independent predictors for BCSS in older women with ER-positive early breast cancer." (PMID 32726924, 2020). "Another subtype of breast cancer is TNBC, which can be characterized by the low expression of estrogen receptor (ER), progesterone receptor (PR) and HER2." (PMID 32570740, 2020). "Immunohistochemistry (IHC) is the most widely employed method to determine the status of ER, PgR, and HER2 in formalin-fixed paraffin-embedded tissue samples of breast cancers." (PMID 32944466, 2020). "TNBC lacks estrogen receptor (ER), progesterone receptor (PR), and HER2 expression and accounts for ~15% of all breast cancer cases." (PMID 33425733, 2020). "We classified breast cancers into three subtypes based on the expression of the estrogen receptor, progesterone receptor, and HER2: 1) HR-positive and HER2-negative breast cancer, 2) HER2-positive breast cancer, and 3) triple-negative breast cancer." (PMID 32176735, 2020). "Further research has revealed that O-GlcNAcylation of progesterone receptor (PR) by OGT transcriptionally activates its target genes, and PR-positive breast cancers express higher levels of OGT." (PMID 33194731, 2020). "Breast cancer diagnosis is carried out by determination by immunohistochemistry of the HER2 receptor, of hormonal receptors (estrogen and progesterone receptor, ER and PR, respectively) and of the proliferation marker Ki67." (PMID 32391269, 2020). "As an invasive breast carcinoma, TNBC is characterized by the absence of expression of the estrogen receptor (ER), progesterone receptor (PgR), and human epidermal growth factor receptor-2 (HER2) proteins that belong to basal cell-like breast cancer." (PMID 32714412, 2020).
breast cancer (continued). "The detection of the estrogen receptor (ER), progesterone receptor (PR) and human epidermal growth factor receptor (HER2) is crucial for prognostic evaluation and treatment choice of breast cancer for clinical practice." (PMID 32471217, 2020). "Evaluation of prognostic and predictive biomarkers ER, PgR, and HER2 is recommended in every case of breast carcinoma." (PMID 32944466, 2020). "The Progesterone Receptor (PR), Estrogen Receptor (ER), and Human Epidermal growth factor Receptor 2 (HER2) are well known predictive markers in breast cancer." (PMID 31908742, 2019). "Among various biomarkers, estrogen receptor (ER), progesterone receptor (PR), and human epidermal growth factor receptor 2 (HER2) play important roles in management and prognosis of patients with breast cancer." (PMID 31583246, 2019). "Estrogen receptor (ER), progesterone receptor (PR) and human epidermal growth factor receptor 2 (HER2) serve as key biomarkers in breast cancer, and their expression in tumor cells forms the basis for endocrine therapy, targeted therapy and disease prognosis." (PMID 31404155, 2019). "Among breast cancers, triple-negative breast cancer (TNBC) sub-type is one of the aggressive breast cancers as TNBC cells lack all three currently targetable molecules such as estrogen receptor, progesterone receptor, and HER2." (PMID 30631046, 2019). "Expressions of the ER, progesterone receptor (PR), and/or human epidermal growth factor receptor 2 (HER2) have long been used for breast cancer classification." (PMID 31293425, 2019). "Various molecular markers, including estrogen receptor (ER), progesterone receptor (PR), human epidermal growth factor receptor-2 (HER2), and Ki67, are widely used in the prognosis of breast cancer and to make treatment-related decisions." (PMID 31998718, 2019). "To examine their estrogenic or antiestrogenic potential, we studied the effect of the flavonoids on viability, progesterone receptor expression and 3xERE/3XERRE-driven reporter gene expression in ERα positive and estrogen responsive MCF-7 breast cancer cells." (PMID 31092862, 2019). "Triple-negative breast cancer (TNBC), which lacks estrogen receptor α (ERα), progesterone receptor, and human epidermal growth factor receptor 2 (HER2) expression, is closely related to basal-like breast cancer." (PMID 31704972, 2019). "Among the 16 patients, six were hormone receptor (Estrogen receptor [ER] and/or Progesterone receptor [PgR]) positive and seven were human epidermal growth factor receptor 2 (HER2) positive as assessed immunohistochemistry in Primary breast cancers." (PMID 31527824, 2019). "The results of network analysis show that RYNXC treat breast cancer by regulating the ESR1, PGR and PTGS2." (PMID 30906412, 2019). "Major breast cancer subtypes including luminal A, luminal B, human epidermal growth factor receptor 2 (HER2)‐enriched and basal‐like were defined by estrogen receptor, progesterone receptor, HER2, and Ki‐67 status." (PMID 30761775, 2019). "Triple-negative breast cancer (TNBC) is a highly aggressive subtype of tumors that lack estrogen receptor (ER), progesterone receptor (PR) and human epidermal growth factor receptor 2 (HER2), which represents 15–20% of all breast cancers." (PMID 31113872, 2019). "Particularly, we identified a novel role for leptin in inducing the generation of exosomes from both estrogen receptor-(ER) and progesterone receptor-(PR) positive MCF-7 and in ER-, PR-, and HER2-negative MDA-MB-231 breast cancer cell lines." (PMID 31336913, 2019). "Around 50% of all HER2-overexpressing breast cancers show the coexistence of both HER2 overexpression/amplification and ER and/or PgR overexpression." (PMID 31470531, 2019). "The degree of agreement among manual and the automated methods (‘Man versus Machine’ comparison) has been published for the scoring of several breast cancer biomarkers, including HER2, ER, PgR and Ki67." (PMID 30796652, 2019).